E2F3 (E2F transcription factor 3)
Diseases named in the same sentence as E2F3 in open-access papers (continued):
Sharing a sentence is not in itself a finding about the gene and the disease.
tumor (continued). "The E2F3 is also highly expressed in the HCC tissues of patients; therefore, matrix stiffness modulates HSC activation into tumor-promoting MYFs via E2F3-dependent MEK/ERK signaling and regulates malignant progression." (PMID 38074679, 2023). "This study demonstrated that miR-363 is able to suppress cell proliferation, migration and invasion by negative regulating E2F3 in CRC cells, and inhibits tumor growth in vivo." (PMID 37283793, 2023). "Gene group 2 displayed a significant upregulation of E2F transcription activators (E2F1, E2F2, E2F3, and E2F6) and tumor-specific transcription factors (MYCN, RUNX1, and GABPB1) in advanced Rb." (PMID 35626705, 2022). "Several ncRNAs, such as miR-491-3p, miR-613,and SUSD2 have been found to act as tumor suppressor genes in RB, but other ncRNAs, such as circ-E2F3, NEAT1, and TUG1 act as tumor promoter genes." (PMID 36619866, 2022). "Four profiles were identified: ‘healthy (H) < tumour-adjacent (TA) < tumour (T), for CIN, GGI, MYC, proliferation and wound response; ‘H < TA = T’ for E2F3; ‘H = TA < T’ for 38-GES, 70-GES, glycolysis, IRGS and PNI; ‘H > TA > T’ for TGFβ." (PMID 33599248, 2021). "Stiffness induces E2F3 nuclear transcription of FGF2, a tumor-promoting factor, to promote HCC growth and metastasis." (PMID 34873170, 2021). "DEP screening in HCT116 cells after NUFIP1 knockdown identified 136 overexpressed and 41 underexpressed proteins, with several of those DEPs (including E2F3, STAT1) involved in regulating tumor growth." (PMID 34367967, 2021). "Inactivation of RB1 expression in tumor cells leads to the deregulation of activity of transcription factors E2F1, E2F2, and E2F3, which control the expression of genes involved in differentiation, development, proliferation, and apoptosis." (PMID 32429447, 2020). "In GSE45436, SNHG11, CRNDE, MYLK‐AS1, E2F3, and CHEK1 were highly expressed in the tumor group, while RASGEF1B was the opposite, which were consistent with the results of TCGA." (PMID 33232580, 2020). "The analysis of the data and IHC in this study found that the expression levels of E2F3 in human PAAD were higher than in normal tissues, and it was related to tumor stage in PAAD patients." (PMID 33604289, 2020). "Further, mRNA E2F3 and CHEK1 were upregulated in the tumor group, which conformed to the ceRNA theory." (PMID 33232580, 2020). "Eight miRNA-449-family target genes (CDC25A, SIRT1, GMNN, E2F1, E2F3, BCL2, CDK2, and CCNE2) were selected; all of them involved in tumor development, cell cycle, and apoptosis." (PMID 30926829, 2019). "In another study, a mechanism of methylation that controlled miR-128-1 expression in GBM cells and GSCs was presently revealed and miR-128-1 functioned as a tumor suppressor in GBM by directly targeting BMI1 and E2F3." (PMID 28947999, 2017). "miR-874-3p has been consistently shown in various tumour types to be a tumour suppressive miRNA through regulation of STAT3, CDK9 and E2F3 expression." (PMID 28076852, 2017). "Ectopic up-regulation of miR-199a-5p/E2F3 contributed to the inhibition of invasion and migration in HCC, accounting for the anti-tumor effect of PPIX." (PMID 28947999, 2017). "The calculated genomic circuit scores were, as expected, high for tumours in the Uro cluster, i.e. FGFR3+, CCND1+, RB1+, and E2F3−, both at the mRNA level and the tumour‐cell protein level." (PMID 28195647, 2017). "We observed a positive correlation of KIF23 expression with a series of tumor oncogenes, driving cell proliferation, mitosis and metastasis, including E2F transcription factor family (E2F1, E2F1, E2F3) and Rhoc." (PMID 27013586, 2016). "In conclusion, our work demonstrated miR-432 plays a tumor-suppressive role in LAD and its function is mainly mediated by its targets, E2F3 and AXL." (PMID 26942465, 2016).
tumor (continued). "Interestingly, PTEN and E2F3 were downregulated after transfection with the miR-26a mimetic; PTEN is one of the most commonly mutated tumor suppressors in cancer and has been shown to negatively regulate the AKT/PKB signaling pathway, favoring tumor development and progression." (PMID 27517917, 2016). "A tumor suppressor miRNA, miR-34a-5p, targeted several critical cancer genes, including CDK6, CCND1, CCNE2, E2F3 in the cell cycle pathway and VEGFA in the angiogenesis pathway." (PMID 27329603, 2016). "We find that in normal samples and superficial tumor samples, the activity for the modules of the E2F1, E2F2 and E2F3 target genes is lower than in invasive tumors, as opposed to the target genes of the inhibitory transcription factors E2F4 and E2F6." (PMID 26925094, 2016). "Thus, we addressed whether rescuing back CA in tumors silenced for E2F3 influenced tumor growth." (PMID 26512919, 2015). "Because miR-195 is involved in repression of cell cycle accelerators (CCND1, CCNE1, CDK4, CDK6, and E2F3) and anti-apoptotic factors (BCL2, BCL2L2, and BIRC5), miR-195 functions as a tumor suppressor miRNA in various types of human cancers." (PMID 25364765, 2014). "Downregulation of anti-tumor (tumor suppressor) miR-125b in human cancers promotes survival, proliferation and invasion of tumor cells through de-repression of BCL2, BCL2L2, E2F3, ERBB2, FGFR2, MCL1, SIRT7, Smoothened and STAT3." (PMID 25364765, 2014). "MAGE-C2/CT-10 should be added to the list of proposed prognostic tumor progression markers, including MUC1, AZGP1, EZH2, E2F3, Ki67, and CD10." (PMID 21754986, 2011). "In accord with previous reports, expression of E2F3 mRNA and DEK mRNA were often increased in tumor compared to normal tissues." (PMID 15876350, 2005). "Applying similar tumor microenvironment oriented analytical strategies to THBS2, CTNNB1, COL4A1, and E2F3 may offer deeper insight into their roles in shaping immune suppression, stromal remodeling, and treatment response in STAD." (PMID 41291892, 2025). "Additionally, E2F3 and E2F7, which are both involved in promoting tumor proliferation and inhibiting apoptosis, exhibited increased expression in high-risk NB, further emphasizing their role in tumor progression." (PMID 40599792, 2025). "Consistent with tumor suppression, effectors of tumorigenesis (Myc, Myb, NKX2-3, and TRIM24), metastasis (NFE2L2), oncogenic transformation (FOXM1), and cell cycle (E2F2 and E2F3) were also inhibited in the presence of PRKN." (PMID 39213189, 2024). "It is speculated that GPD1L overexpression in HCC may be a consequence of promoter demethylation and the wider E2F dysfunction with advancing tumour stage, where GPD1L itself is an E2F3 target." (PMID 37685919, 2023). "E2F3 was negatively correlated with DBNDD1 expression in normal prostate tissues but showed no significance in tumor tissues." (PMID 37569304, 2023). "Highly expressed E2F3 in NPC cells activates transcription of PRC1 and BIRC5, which renders an immunosuppressive TME characterized by abundant M2 TAMs to trigger the growth and metastasis of tumor cells." (PMID 37647439, 2023). "We then investigated the relationships between the eight E2Fs and tumor immunology and found that E2F1, E2F3, E2F5, E2F6, and E2F7 expression was positively correlated with many immune cells, which might explain their favorable prognostic value." (PMID 34617871, 2021). "E2F3 enhances the malignant properties of ESCC cells, and overexpression of E2F3 could reverse the tumor-suppressing functions of miR-140-3p." (PMID 33680929, 2020).
tumor (continued). "As control cell (ARPE19 and SV-HUC-1) were immortal cell lines without defined biologic relationship with corresponding tumor cell lines, the biologic comparison of E2F3 expression in tumors and control cell lines should be further determined." (PMID 32669100, 2020). "Specifically, ChIRP-PCR showed that RBAT1 was enriched in the E2F3 promoter region in three tumor cell lines, whereas a weak RBAT1 enrichment was observed at the E2F3 promoter after RBAT1 suppression; suggesting that the promoter region of E2F3 was the binding site for lncRNA RBAT1." (PMID 32669100, 2020). "In our report, we demonstrated that the expression of E2F3 in LC tissues was higher than that in normal tissues, but this expression was not correlated with tumor stage in patients with LC." (PMID 29754146, 2018). "In addition, miR-874 is involved in tumor progression by suppressing the protein levels of MMP-2 and uPA and targeting E2F3, HDAC1, AQP3 STAT3 and HCA587/MAGE-C2 in a variety of cancers." (PMID 28525377, 2017). "The propensity of E2F3 and HIF-2α in the same cellular location (cytoplasm) of ccRCC indicated that they may cooperate to facilitate tumor progression but the mechanism still needs to be explored." (PMID 28903320, 2017). "Meanwhile, miR-217 was reported to function as a tumor suppressor in HCC progression and miR-217/E2F3 and miR-214/E2F3 axises may be potential candidates for developing rational therapeutic approaches." (PMID 28947999, 2017). "For example, in one patient treated with neoadjuvant gemcitabine and cisplatin with no response to treatment, rapid recurrence and short survival, we identified amplification in focal segments containing E2F3 and JUN (drivers of cell cycle progression) exclusively in the post-treatment tumor sample." (PMID 29259186, 2017). "In contrast, sar@LIP induced the up-regulation of a broad spectrum of genes related to the positive induction of cell proliferation (CCND1, E2F3, PDGFRB and TEGT, a described BAX inhibitor), which corresponds to the tumor growth enhancement observed in vivo after sar@LIP administration." (PMID 27646588, 2016). "NEAT1 acts as an oncogene to promote tumor progression in NSCLC in large part attributed to its ability to inhibit miR-377-3p (acting as “competitive endogenous RNAs (ceRNAs)”) and subsequent activation of the E2F3 signaling pathway." (PMID 27351135, 2016). "Moreover, PPIX at the dose of 0.3 or 1.0 mg/kg suppressed the induction of E2F3, Ki-67, and CD31 in the xenograft tumors, verifying the ability of PPIX to inhibit tumor cell proliferation and angiogenesis." (PMID 25714015, 2015). "We postulate that restriction of mitosis is the primary mechanism suppressing tumor growth, since silencing E2F3 did not alter the percentage of tumor cells undergoing proliferation." (PMID 26512919, 2015). "Furthermore luminal tumours express high levels of GATA3 and ER similar to luminal breast cancers and basal like tumours display enhanced MYC and E2F3 pathway signatures." (PMID 26316886, 2015). "Overall, these cells were rare and our analysis shows that E2f1 is able to largely rescue both the tumor and developmental phenotype, E2f3 is able to rescue the tumor phenotype but not the developmental phenotype and E2f5 can rescue neither." (PMID 25338120, 2014). "Interestingly, when adding the E2F3 expression to the FANCA and BRCA1 gene expression correlation, tumor samples with relatively low expression of FANCA and BRCA1 had also low E2F3 and vice versa." (PMID 25161863, 2014). "In addition, tumor samples from HNSCC patients showed an inverse relationship between miR-34a and survivin as well as miR-34a and E2F3 levels." (PMID 22629428, 2012). "Whereas the absence of E2F1 and E2F3 function has no impact on Myc-mediated tumor development, the absence of E2F2 substantially accelerates the time of tumor onset." (PMID 19749980, 2009).
tumor (continued). "This probably indicates that E2F3 is upregulated early in tumour development and hence not directly related to the outcome of the disease." (PMID 19156145, 2009). "Interestingly, E2F1, E2F3 and E2F5 were present on this supervised gene list and highly expressed in tumours with RB1 LOH." (PMID 18782450, 2008). "However, E2F3 expression was not correlated with the clinical characteristics and tumor progression of HNSCC." (PMID 36855110, 2023). "Moreover, the expression of E2F3 was significantly positively correlated with the levels of circ_0087378, while E2F3 expression was negatively correlated with the levels of miR-140-3p in ESCC tumor tissues." (PMID 33680929, 2020). "In the data sets analyzed in this work, only 9 stage 4S NB patients presented MYCN amplified tumor; however, we could not analyze either the E2F3 expression or its relation with survival of this group of patients." (PMID 32429447, 2020). "Indeed, the tumor Pi-ATAC data demonstrate a significant increase of DNA accessibility of motifs for Fox family and E2f3 in the cells with high HIF1α protein (Wilcoxon test p < 0.05) in a more detailed comparison of TF motif accessibility across the three groups." (PMID 30389926, 2018). "Moreover, miR-503 functioned as a tumor suppressor in HCC by directly targeting cyclin D3 and E2F3 through Rb-E2F signaling pathway, suggesting that miR-503/E2F3 may act as helpful therapeutic targets for HCC therapy." (PMID 28947999, 2017). "However, transgenic mice expressing inducible E2F3 resulted in hyperplasia, but not tumor development, supporting its role in tumor progression rather than initiation." (PMID 29104726, 2017). "Our results revealed a mechanism of methylation that controls miR128-1 expression in GBM cells and GSCs and indicate miR128-1 could function as a tumor suppressor in GBM by negatively regulating tumor cell proliferation, invasion and self-renewal through direct targeting BMI1 and E2F3." (PMID 27705931, 2016). "In addition to EMT regulation, the well-known property of miR-34a is its tumor suppressor function via inducing cell cycle arrest and apoptosis in various cancer types by targeting several molecules crucial for sustaining tumor growth such as CDK4/6, MET, HDAC1, E2F3 and Bcl-2." (PMID 25614041, 2015). "Moreover, miR-503 has been widely described in the literature as an anti-tumor miRNA that regulates the expression of key cell cycle proteins, such as CDC25A and cyclins D1 and E1, as well as cell proliferation via E2F3 and PI3K regulation and the apoptosis status via BCL-2 inhibition." (PMID 25860935, 2015). "Notably, regulatory pairs such as E2F3/5/7: gga-miR-106-5p/gga-miR-15c-5p/gga-miR-16c-5p/gga-miR-20b-5p/gga-miR-449 family and PTEN: gga-miR-363-3p/gga-miR-92-3p/gga-miR-29b-3p/gga-miR-148-3 were identified, emphasizing their crucial role in cell cycle control and tumor suppression." (PMID 38278859, 2024). "Moreover, RBAT1 may activate E2F3 and interact with HNRNPL to promote tumor progression." (PMID 37501162, 2023). "However, the fascinating observation of our study is that the hub genes including CDK1, CDK2, CCNB1, and HDAC1 and common genes including E2F3 identified in Rb tissues are well-known oncogenes that trigger cell cycle progression in tumor cells in the absence of RB1 gene." (PMID 35359459, 2022). "Furthermore, tumor angiogenesis was found to be dysregulated by interference of miR-34a with VEGF secretion in tumor cells, as well as EC proliferation, migration, and tube formation, by downregulating a number of key proteins including E2F3, SIRT1, survivin, and CDK4." (PMID 30717449, 2019). "When we examined the mRNA expression levels of several tumor metastasis-related genes after knocking down HOXB9 (data not shown), we only found E2F3 mRNA expression levels were decreased significantly." (PMID 29724991, 2018).
tumor (continued). "Mechanistically, conditional knockout of E2F3 in mammary epithelial cells diminished the average percentage of cells within ERBB2 tumors undergoing S phase, but this deletion had no impact on tumor growth rates." (PMID 26512919, 2015). "No immunoreactivity for KIF14 or E2F3 was noted in the control healthy retina, whereas KIF14 expression was localized to the nucleus and cytoplasm in tumor cells, and E2F3 expression was localized to the nucleus." (PMID 19190782, 2009). "The results showed that the expression levels of E2F2, E2F3, E2F6, and E2F8 are significantly correlated with the tumor stage of PAAD patients, while the expression levels of E2F1, E2F4, E2F5 and E2F7 are not correlated with the tumor stage of PAAD patients." (PMID 33604289, 2020). "To confirm if the DNA accessibilities of tumor cells, particularly HIF, Fox, E2f3, Atoh, Pit1 motifs, are indeed modulated by hypoxia and no other tumor microenvironmental stimuli, we used an in vitro cell line culture system to simulate the in vivo hypoxia microenvironment." (PMID 30389926, 2018).